ANK3 (ankyrin 3)
Diseases named in the same sentence as ANK3 in open-access papers (continued):
Sharing a sentence is not in itself a finding about the gene and the disease.
neurodevelopmental disorder (12 papers, 2013 to 2025). A behavioral and cognitive disorder with onset during the developmental period that involves impaired or aberrant development of intellectual, motor, or social functions. "While both monoallelic and biallelic ANK3 variants have been linked to neurodevelopmental disorders (NDDs), existing evidence for their pathogenicity and clinical correlation remains limited and heterogeneous." (PMID 40879451, 2025). "Variants in the ANK3 gene encoding ankyrin-G are associated with neurodevelopmental disorders, and ankyrin-G is enriched in postsynaptic density fractions and facilitates synapse formation." (PMID 33483467, 2021). "Among them, ANK3 plays an important role in coordinating appropriate action potential initiation and axonal propagation, and genetic variations in the ANK3 gene are associated with human neurodevelopmental disorders." (PMID 39600307, 2024). "In addition, heterozygous loss-of-function (LOF) variants affecting all brain-specific isoforms of ANK3 have been identified in individuals affected by a neurodevelopmental disorder." (PMID 34218362, 2021). "Our CoIP/MS analysis suggests that iASPP may directly associate with some proteins that are involved in nervous system development and neurodevelopmental disorders, such as Ank3 and Sptan1." (PMID 37284462, 2023).
tumor (12 papers, 2011 to 2025). "This study demonstrated that changes in subcellular localization of ANK3 in PTC cells had important effects on maintaining PTC as an indolent tumor." (PMID 35646694, 2022). "Results showed that mice injected with ANK3-stably overexpressing TPC-1 cells exhibited smaller tumor volumes and lighter tumor weights compared to the control group (P < 0.05)." (PMID 35646694, 2022). "In another example, high levels of ANK3 suppress tumor cell invasion." (PMID 34880267, 2021). "ANK3 seems to be the most solid candidate, being predicted by 3 out of 4 programs: in particular, it results a suitable target for miR-182, which is greatly up-regulated at 11 months in tumor samples compared to controls." (PMID 26652480, 2015). "Notably, significant functional differences are predicted between the long or short isoforms of TCF12, OSBPL1A, TRAK1, CHEK1, ANK3, LMO7 and SCIN indicating that the observed tumor associated changes in TSS usage probably have an impact on the growth properties of the neoplastic cells." (PMID 21999571, 2011). "Most of the genes were down-regulated in tumor tissues, for example, EDN3, KCNA1, TFAP2B, and ANK3 genes were significantly down-regulated in KICH, COAD, HNSC, KIRC, THCA, and KIRP." (PMID 41174507, 2025). "A comparative analysis revealed that five sodium ion transport-related genes—FXYD2, ANK3, ATP1A1, PRSS8, and CHP1—were significantly downregulated in malignant cells, implicating their potential involvement in tumor suppression." (PMID 40723891, 2025). "Moreover, in the present study, we also revealed that ANK3 expression restrained tumor cell invasiveness and suppressed the epithelial- mesenchymal transition (EMT) of PTC cells through increased E-cadherin expression and it could be an indolent maintainer of PTC." (PMID 35646694, 2022). "The 5 genes (TTC39C, HSPBP1, MAZ, ANK3 and ZC3HAV1) where model AS events occurred were analyzed for the differential expression level between normal breast tissue and tumor tissue." (PMID 35988113, 2022). "To further explore the expression of ANK3 in PTC tissues, we conducted immunohistochemistry staining for ANK3 on four PTC microarrays containing 110 pairs of PTC samples and the corresponding tumor-adjacent tissues." (PMID 35646694, 2022). "The existence of a physical link for Ankyrin G and HOOK1 provide thus an additional clue to the hypothesized role of ANK3 in the regulation of EMT for tumor metastases." (PMID 26652480, 2015).
neurological disorders (4 papers, 2014 to 2025). "SAFB1 mediated isoform-specific changes in ANK3, ANKS1B, SAP97 (DLG1), ADD2, KIF16B, and ELK3, as well as in genes linked to the cytoskeleton and/or synaptic function and the aetiology of neurologic disease." (PMID 26694817, 2015).
inflammation (1 paper, 2021). Aberrant reaction of the microcirculation characterized by movement of fluid and leukocytes from the blood into extravascular tissues. "For example, the switch of diet from FO to VO was particularly strongly associated with expression of hM104, which contains the ankyrin-3 gene (ank3) that alters Na-K-ATPase activity during chronic intestinal inflammation." (PMID 33613868, 2021).
metabolic disorders (1 paper, 2017). "Notably, four of seven methylation loci were located in coding genes (ANK3, CDKN2B, CACNA1G) and the miRNA let-7b host gene (MIRLET7BHG) that have been previously implicated in metabolic disorders in human adults and animal model systems." (PMID 28264723, 2017).
movement disorder (1 paper, 2021). Neurological conditions resulting in abnormal voluntary or involuntary movement, which may impact the speed, fluency, quality and ease of movement. "Since a stereotypic movement disorder (SMD) was not formally diagnosed, it remains difficult to differentiate between SMD and stereotypic autistic behavior—but stereotypic limb movements might represent a novel ANK3-related symptom." (PMID 34218362, 2021).
neurodegenerative disease (1 paper, 2022). A disorder of the central nervous system characterized by gradual and progressive loss of neural tissue and neurologic function. "Our analysis of the AD interactome indicates that 14-3-3G interacts directly with tau (TAU) and other aggregate proteins, including ankyrin-3 (ANK3), plectin (PLEC), kinesin heavy chain 5C (KIF5C), and hexokinase (HXK1) —all of which play key roles in neurodegenerative-disease aggregation." (PMID 36555098, 2022).
ANK3 also shares sentences with these, for which no sentence is quoted: Arrhythmia (5 papers); prostate carcinoma (3); Brugada syndrome (2); cardiac arrhythmia (2); cardiovascular disease (2); Cerebellar Ataxia (2); dilated cardiomyopathy (2); myocardial infarction (2); psychosis (2); adenoma (1); Arthritis (1); astrocytoma (1); atrial fibrillation (1); bronchial hyperreactivity (1); cataract (1); central nervous system diseases (1); cervical cancer (1); chronic sinusitis (1); cleft lip (1); cognitive decline (1); COVID-19 (1); cutaneous melanoma (1); demyelination (1); endometriosis (1); glioma (1); Hashimoto thyroiditis (1); head and neck squamous cell carcinoma (1); hypopharyngeal cancer (1); Intracranial Aneurysm (1); ischemia (1).
A further 22 diseases each share a sentence with ANK3 in 1 paper.